TET2 (tet methylcytosine dioxygenase 2)
Diseases named in the same sentence as TET2 in open-access papers (continued):
Sharing a sentence is not in itself a finding about the gene and the disease.
Myelodysplasia (15 papers, 2013 to 2025). Clonal hematopoietic stem cell disorders characterized by dysplasia (ineffective production) in one or more hematopoietic cell lineages, leading to anemia and cytopenia. "Altogether, Zrsr2 and Tet2 mutations cause a phenotype that recapitulates critical features of myelodysplasia." (PMID 36030305, 2022). "In another model, concurrent deletion of Tet2 and Ezh2 cooperated to cause more advanced myelodysplasia and accelerated the development of myeloid disorders including MDS/MPN." (PMID 30450160, 2018). "We studied the association between the TET2 mutational status and 5hmC levels in bone marrow samples obtained from patients with myelodysplasia." (PMID 25276435, 2014). "We also present DNA methylation data from bone marrow samples obtained from patients with TET2-mutated myelodysplasia." (PMID 25276435, 2014). "Mice models have revealed that EZH2 or TET2 deficiency alone is sufficient to induce an MDS/MPN phenotype with lethality, while depletion of both EZH2 and TET2 synergistically induces myelodysplasia and strengthens the progression of both MDS and MDS/MPN." (PMID 36338673, 2022). "These preleukemic HSCs harbor mutations associated with myelodysplasia (e.g., of DNMT3A, TET2, and others), which persist in myeloid cells as well as B and T cells but lack the mutations present in leukemic blasts." (PMID 35259128, 2022). "Additionally, recent data demonstrated that myeloid specific mutations including TET2, ASXL1, and DNMT3A can induce inflammasome activation in myelodysplasia and exacerbate inflammation." (PMID 33648567, 2021). "tet2 MO-based knockdown in zebrafish results in mild defects in erythropoiesis; however, mutations in tet2 do not cause any overt embryonic phenotype, although tet2-/- adults develop progressive age-related clonal myelodysplasia." (PMID 28926578, 2017).
thrombosis (15 papers, 2013 to 2025). "Together with the currently available resources, these datasets allow for the understanding of molecular mechanisms of the effect of TET2 mutations on the risk of thrombosis and open the prospect of the discovery of new targets and biomarkers for VTE." (PMID 41169875, 2025). "Pathogenic DTA gene mutations (p = 0.02), especially TET2 gene mutation (p = 0.03), were found to be significantly accompanied by the development of thrombosis in the PV group." (PMID 36611455, 2023). "Our study, likewise, demonstrated that TET2 remained an independent risk factor for thrombosis in ET patients with age, cardiovascular risk factors, and previous thrombosis as covariates, again an association not observed in PV." (PMID 36431092, 2022). "Further, studies have shown that patients with initial JAK2 mutation demonstrated a higher risk of thrombosis compared to a more indolent course in patients with initial PV-associated TET2 mutation." (PMID 34660059, 2021). "Specifically, mutations in the TET2 gene in isolation were also associated with thrombosis in the PV case-control cohort." (PMID 32290079, 2020). "Another study also highlighted that there may be an association between the history of thrombosis and the presence of TET2, DNMT3A, or ASXL1 mutations." (PMID 37745842, 2023). "In an age-matched case–control study of PV patients, investigators observed that the presence of ≥1 TET2 or ASXL1 or DNMT3A mutations significantly increased the risk of thrombosis, and that PV patients with a TET2 mutation had a significantly higher risk of thrombosis." (PMID 36431092, 2022). "A previous study reported a possible association between TET2 mutations and thrombosis in ET." (PMID 32290079, 2020). "This was recently demonstrated for patients with JAK2 and TET2 double mutated polycythemia vera, where the individuals who had first acquired a JAK2 mutation had a higher risk of thrombosis and responded better to ruxolitinib than those who had first gained a TET2 mutation." (PMID 29740158, 2018). "This may explain why TET2 mutations are a risk factor for thrombosis in ET patients." (PMID 41169875, 2025). "Taken together, TET2 mutation may increase the risk of thrombosis in patients with PV." (PMID 36611455, 2023). "Our study showed that TET2 mutation is an independent risk factor for thrombosis in ET patients, and to understand their clinical characteristics and coagulation status, we compared the clinical characteristics and coagulation functions of TET2-mutated and -unmutated patients." (PMID 36431092, 2022). "Therefore, TET2 mutation may be more valuable in predicting thrombosis in ET patients compared to PV." (PMID 36431092, 2022). "For example, the current risk algorithm for patients with PV, stratified into low risk (<60 years, no history of thrombosis) and high risk (>60 years and/or history of thrombosis) could be modified to include a third very high-risk group (>60 years and/or history of thrombosis with a TET2 mutation)." (PMID 32290079, 2020). "The TET2 gene serves as a critical regulator in venous thrombosis by modulating the interaction of coagulation factors." (PMID 41169875, 2025). "Only TET2 missense mutations were significantly associated with prior arterial thrombosis, while BCOR mutations were significantly associated with prior venous thrombosis." (PMID 40533498, 2025). "TET2 (Ten-Eleven Translocation 2) plays an essential role in regulating platelet function, which is involved in venous thrombosis." (PMID 41169875, 2025). "Several lines of evidence indicate that mutations in JAK2, MPL, TET2 and ASXL1 gene and polymorphisms in several clotting factors (GPIa, GPIIa, and GPIIIa) are associated with the occurrence and prevalence of thrombosis in MPN patients." (PMID 36611455, 2023). "Compared with patients in whom TET2 mutation was acquired first, patients in whom the JAK2 mutation was acquired first had an increased risk of thrombosis and a poor prognosis." (PMID 33653301, 2021).
thrombosis (continued). "Among patients with variations associated with CHIP (DNMT3A, TET2, ASXL1, JAK2), thrombosis occurred in 5 patients (62%; odds ratio [OR], 5.6; 95% CI, 1.3-15.9) and death in 3 patients (37%; OR, 6.1; 95% CI, 1.3-26.9)." (PMID 34357393, 2021). "Our study also showed that previous thrombotic history and NLR were independent risk factors for thrombosis in PV patients, and that TET2 or ASXL1 did not affect thrombosis in PV patients, even in the univariate analysis." (PMID 36431092, 2022). "Our data suggest that TET2 mutation is an independent risk factor for thrombosis in ET patients, but no such association is observed in PV." (PMID 36431092, 2022). "Therefore, we speculate that targeted TET2 therapy could also be applied to the prevention and treatment of venous thrombosis." (PMID 41169875, 2025). "TET2 or ASXL1 mutations did not impact arterial nor venous thrombosis." (PMID 29282357, 2017). "As far as the 25 thrombotic events in patients without TET2, 3 portal vein thrombosis, 1 Budd-Chiari syndrome, 4 strokes, 2 deep vein thrombosis, and 13 acute myocardial infarctions were recorded." (PMID 23781511, 2013). "Additionally, the non-driver TET2 and ASXL1 mutations did not impact arterial nor venous thrombosis." (PMID 29282357, 2017).
Hyperglycemia (14 papers, 2016 to 2025). An increased concentration of glucose in the blood. "Blockade of NLRP3 inflammasome–mediated secretion of IL-1β in TET2-deficient immune cells using MCC950 suppressed the higher levels of IL-1β and increased hyperglycemia and IR in mice carrying TET2-deficient HSCs." (PMID 37071471, 2023). "In conclusion, we showed for the first time that the expression of 5-hmC and TET2 was downregulated in CRC with hyperglycemia and insulin resistance associated with visceral fat obesity in this study." (PMID 36806702, 2023). "Chronic infection with HIV was associated with several pLMs53 and hyperglycemia contributed to the evolution of TET2 preL-HSPCs54." (PMID 37045808, 2023). "Under hyperglycaemia, more TET2 proteins were degraded due to the loss of its phosphorylation by AMPK, resulting in epigenomic reprogramming." (PMID 33551821, 2020). "Hyperglycemia can directly rewire the epigenome towards an oncogenic state: hyperglycemia abolishes the AMPK-mediated phosphorylation of the tumor suppressor (TET2)." (PMID 38831236, 2024). "The FITC-dextran transendothelial assay results were similar to those of the TEER assay: TET2 shRNA effectively inhibited the hyperglycemia-induced increase in HREC monolayer permeability." (PMID 37430272, 2023). "Furthermore, the effect of hyperglycemia on the binding activity of TET2 to the ROBO4 promoter in HRECs was detected by ChIP." (PMID 37430272, 2023). "Compared with the control group, the ZO-1 and occludin protein expression levels were significantly decreased in the hyperglycemia group, and were significantly increased in the TET2 shRNA transfection group, as compared with the control shRNA transfection group." (PMID 37430272, 2023). "The effects of hyperglycemia on DNA methyltransferase 1, Tet methylcytosine dioxygenase 2 (TET2), 5-methylcytosine, 5-hydroxymethylcytosine, and the binding of TET2 and SP1 to the ROBO4 promoter, as well as the expression of ROBO4, zonula occludens 1 (ZO-1) and occludin were examined." (PMID 37430272, 2023). "Investigating whether hyperglycaemia affects the phosphorylation of 2-OGDD members other than TET2, and the effects of this on endothelial cell function, could be a valuable area of study." (PMID 32345373, 2020). "Silencing of TET2 could prevent hyperglycemia-induced increase in 5hmC and MMP-9 transcription." (PMID 30987683, 2019). "A similar trend was observed in the western blotting assay, where TET2 shRNA transfection downregulated the hyperglycemia-induced elevated ROBO4 and TET2 protein expression levels." (PMID 37430272, 2023). "We found that hyperglycemia upregulated the transcript levels of ROBO4, DNMT1 and TET2, in an exposure time-dependent manner." (PMID 37430272, 2023). "Hyperglycemia reduces the activity of a cellular energy sensor called adenosine monophosphate-activated protein kinase (AMPK), induces instability of TET2, and promotes carcinogenesis." (PMID 36806702, 2023). "In vitro, hyperglycemia stimulation increased HREC monolayer permeability, enhanced HREC migratory ability, and reduced HREC tube-formation ability, while TET2 depletion effectively improved these HREC dysfunctions." (PMID 37430272, 2023). "Additionally, after inhibiting TET2 expression by shRNA, the oxidation of 5mC to 5hmC and SP1 binding to ROBO4 decreased, which regulated the abnormal hyperglycemia-induced increase in ROBO4 and returned ROBO4 expression to almost normal levels." (PMID 37430272, 2023). "Endothelial cells exposed to transient hyperglycemia (7 days) are characterized by the persistence of NFκB-p65 gene (RELA) activation, induced by DNA demethylation of the NFκB promoter at CpGs islands through TET2 upregulation." (PMID 35562979, 2022).
Hyperglycemia (continued). "Studies have found that hyperglycemia in T2DM patients triggers a self-regulatory mechanism leading to the reduction of 5mC levels in the peripheral blood, which indicates that the DNA might undergo demethylation via the upregulation of ten-eleven-translocation 2 (TET2), a DNA demethylation enzyme." (PMID 34025445, 2021).
Insulin resistance (14 papers, 2021 to 2025). Increased resistance towards insulin, that is, diminished effectiveness of insulin in reducing blood glucose levels. "In a mouse model, clonal hematopoiesis driven by somatic TET2 mutation aggravates insulin resistance in mice." (PMID 38305890, 2024). "Tet2 loss-of-function-driven clonal hematopoiesis showed a progressive aggravation of insulin resistance and an increase in fasting blood glucose levels in aged, obese mice." (PMID 37457265, 2023). "Mutations like TET2 lead to increased inflammation in adipose tissue, driving insulin resistance." (PMID 40214958, 2025). "Moreover, the presence of TET2 mutation in CHIP was found to be linked with increased insulin resistance in obese and elderly mice." (PMID 37374147, 2023). "TET2 has been suggested to facilitate the transcriptional activity of peroxisome proliferator-activated receptor gamma (PPARƴ), involved in insulin sensitivity; thus, a TET2 loss-of-function may have promoted insulin resistance." (PMID 36009574, 2022). "TET2 deficiency-related CHIP elevates macrophage-derived IL- 1β in white adipose tissue, exacerbating insulin resistance in obese or aged mice, in line with a significant association between TET2 (HR 1.48; CI 1.05–2.08) and type 2 diabetes." (PMID 40214958, 2025). "These inflammatory cytokines contribute to the development of CVD and insulin resistance, as observed in TET2-mutant mice." (PMID 40214958, 2025). "TET2, as one of the commonly mutated genes in MDS, has been found to be connected with insulin resistance, but the correlation between the gene mutation and DM in MDS patients has not yet been clearly indicated." (PMID 38305890, 2024). "Therefore, TET2 plays an active role in the pathogenesis of insulin resistance in adipose tissue." (PMID 36806702, 2023).
Splenomegaly (14 papers, 2015 to 2024). Abnormal increased size of the spleen. "Taken together, these data suggest that TET2 loss could predispose to myeloid disease characterized by splenomegaly and extramedullary disease in general, which is mutant TET2 gene dosage dependent, although investigation in large patient cohorts is warranted." (PMID 36480300, 2023). "Consistent with this, young, healthy mice null for Tet2 have elevated extramedullary hematopoiesis in the spleen, which develops into splenomegaly concomitant with the onset of myeloid dysplasia." (PMID 36480300, 2023). "At greater than 60 weeks of age, Tet2-KO mice display splenomegaly which trends towards reduction in DKO mice." (PMID 38062031, 2023). "The results demonstrated that TET2-KO mice exhibited marked splenomegaly, while the thymus of TET2-KO mice showed similar histological features to those of WT mice." (PMID 35490157, 2022). "Control Tet2+/− mice receiving water, spontaneously developed splenomegaly and increased proportion of Gr-1+/Mac-1+ myeloid lineage cells in the peripheral blood (PB), spleen and BM." (PMID 32895473, 2020). "Mice with Treg-specific deletion of Tet2 and Tet3 (Tet2/3fl/flFoxp3Cre mice) display defective Treg function and develop an inflammatory disease characterized by splenomegaly and leukocyte infiltration into tissues." (PMID 31043609, 2019). "Ezh2 knockout mice (Ezh2−/−) developed myelodysplastic disorders characterized by anemia, splenomegaly, and dysplasia of the bone marrow, and the concurrent loss of both Tet2 and Ezh2 resulted in either an MDS phenotype (pancytopenia, myelodysplasia) or MDS/MPN phenotype (monocytosis, splenomegaly)." (PMID 38396286, 2024). "Furthermore, Tet2–/– mice with myeloid disease also have more pronounced splenomegaly compared with heterozygous (Tet2+/–) littermates, and splenomegaly (and extramedullary disease) is a general feature of myeloid disease developing in Tet2-knockout mouse models." (PMID 36480300, 2023). "Here we show that mutations of Zrsr2 and Tet2, genes commonly co-mutated in human MDS, resulted in impairment of myelo-erythroid differentiation and the development of thrombocytopenia and anemia, multi-lineage dysplasia, and splenomegaly with extramedullary hematopoiesis." (PMID 36030305, 2022). "The resultant mice with germline deletion of Tet2 are viable and fertile but develop a CMML-like disease with leukocytosis, neutrophilia and monocytosis along with increased bone marrow cellularity, splenomegaly, and moderate liver enlargement." (PMID 35756660, 2022). "In all Tet2/3 DKO mice, myeloid expansion was accompanied by massive, progressive splenomegaly and hepatomegaly." (PMID 26607761, 2015). "The resulting mice (Tet2fl/fl) were then crossed with transgenic Vav-Cre mice, resulting in Tet2 deletion in the hematopoietic system in utero, leading to the development of a CMML-like disease by 20 weeks of life with monocyte–predominant leukocytosis and splenomegaly." (PMID 35756660, 2022). "Moreover, it was shown that transplantation of Tet2 -/-, but not wild-type (WT) or Tet2 +/- BM cells, was associated with elevated white blood cell (WBC) counts, monocytosis and splenomegaly in WT recipient mice." (PMID 34660314, 2021). "Decreased TET2 and TET3 was shown to compromise physiological Treg function in animal experiments in which mice lacking TET2 and TET3 in Treg cells develop inflammatory disease with splenomegaly and leukocyte infiltration into the lung." (PMID 35386689, 2022).